PRAME (PRAME nuclear receptor transcriptional regulator)
Diseases named in the same sentence as PRAME in open-access papers (continued):
Sharing a sentence is not in itself a finding about the gene and the disease.
liver cancer (2 papers, 2023). An epithelial or non-epithelial malignant neoplasm that arises from the liver. "To translate data from cellular models into HCC patients, we studied transcript levels of PRAME in publicly available liver cancer datasets focusing on its expression in normal tissue versus HCC, as well as PRAME expression in the context of histological grade and invasive phenotype." (PMID 37173882, 2023). "PRAME expression fostered the migratory and invasive potential of various liver cancer cell lines." (PMID 37173882, 2023). "In contrast, PRAME negatively correlated with FOXA2 and AR expression in human liver cancer cell lines." (PMID 37173882, 2023).
non-melanoma skin carcinoma (2 papers, 2022 to 2024). "In fact, MCC was found to be the second most common non-melanoma skin cancer to show some degree of PRAME expression (57% of lesions) and the most common NMSC tested showing staining in more than 25% of lesions." (PMID 38338862, 2024). "PRAME has not been as widely researched in non-melanoma skin cancers (NMSCs)." (PMID 38338862, 2024).
sebaceous carcinoma (2 papers, 2024). "Of note, BCC, SCC, and sebaceous carcinoma all showed low levels of PRAME immunoreactivity, with varying percentages of cases showing nuclear staining (BCC 59.4%, SCC 37.1%)." (PMID 38338862, 2024).
serous adenocarcinoma (2 papers, 2009 to 2024). An adenocarcinoma that is characterized by the presence of papillary patterns and cellular budding. "We analysed the gene expression of CLU, ITGB3, CAPG, and PRAME in 30 advanced staged serous adenocarcinomas with quantitative real-time polymerase chain reaction (QPCR) and the protein levels were analysed in 98 serous adenocarcinomas with western blot for semiquantitative analysis." (PMID 19775429, 2009).
serous ovarian carcinoma (2 papers, 2019 to 2020). "Promoter hypomethylation and expression of PRAME correlates with increased survival in high grade serous ovarian carcinoma." (PMID 31608277, 2019).
small cell lung carcinoma (2 papers, 2021 to 2026). Small cell lung cancer (SCLC) is a highly aggressive malignant neoplasm, accounting for 10-15% of lung cancer cases, characterized byrapid growth, and early metastasis. "IMC-F106C targets PRAME and is being tested in a phase I clinical trial (NCT04262466) in the following different tumors: breast, endometrial, ovarian, and small-cell lung cancer." (PMID 34885078, 2021).
thymoma (2 papers, 2020 to 2022). A neoplasm arising from the epithelial cells of the thymus. "In conclusion, our results suggested that PRAME may be a novel diagnostic marker differentiating TSQCC from thymoma." (PMID 32704057, 2020). "Five of 34 (14.7%) type AB, one of 28 (3.5%) type B2, and two of 17 (11.8%) type B3 thymomas showed positive staining for PRAME." (PMID 32704057, 2020). "Although some cases of types AB, B2, and B3 thymomas (14.7%, 3.5%, and 11.8%, respectively, in this study) showed positivity for PRAME, the staining pattern was focal and weak." (PMID 32704057, 2020). "All 17 (100%) TSQCCs displayed diffuse and strong PRAME expression, whereas eight of 116 (6.8%) thymomas displayed focal and weak expression (p < 0.0001)." (PMID 32704057, 2020). "We then examined PRAME expression in 17 TSQCCs and 116 thymomas via immunohistochemistry." (PMID 32704057, 2020). "However, in this study, we clearly demonstrated the upregulation of PRAME mRNA in TSQCCs compared with that in normal control samples and the overexpression of PRAME protein in TSQCCs compared with that in thymomas and normal control samples." (PMID 32704057, 2020). "In addition, PRAME-positive thymomas are always KIT- and CD5-negative." (PMID 32704057, 2020). "This study showed that of the 17 cases of TSCC and 116 thymomas in which PRAME expression was detected by immunohistochemistry, all 17 cases (100%) of TSCC showed diffuse strong expression of PRAME." (PMID 36088333, 2022). "Diffuse and strong expression of PRAME was observed in TSQCC, which was distinct from that in thymoma." (PMID 32704057, 2020). "The KIT-/CD5-positive type B3 thymoma was negative for PRAME." (PMID 32704057, 2020). "Importantly, all TSQCCs showed diffuse and strong expression of PRAME, whereas thymomas showed no expression or only focal and weak expression." (PMID 32704057, 2020). "Furthermore, metastatic lesions of PRAME-positive thymomas (n = 4) showed no expression of PRAME, in contrast to metastatic lesions of TSQCC (n = 1), which showed strong and diffuse expression of PRAME." (PMID 32704057, 2020). "No cases of type B3 thymoma showed simultaneous positivity for PRAME, KIT, and CD5." (PMID 32704057, 2020).
uterine carcinosarcoma (2 papers, 2017 to 2020). A usually aggressive malignant neoplasm arising from the uterine corpus and less often the cervix. "We determined that uterine carcinosarcoma, a disease that lacks standard therapies, highly overexpresses the PRAME antigen." (PMID 28630682, 2017). "Furthermore, PRAME expression was significantly higher (p < 0.001) in uterine carcinosarcoma than in normal uterus (n = 83)." (PMID 28630682, 2017).
acute promyelocytic leukemia (1 paper, 2019). An aggressive form of acute myeloid leukemia (AML), characterized by arrest of leukocyte differentiation at the promyelocyte stage, due to a specific chromosomal translocation t(15;17) in myeloid cells. "However, whether the increased expression of PRAME could be linked to resistance to all-trans retinoic acid (ATRA) therapies in patients with acute promyelocytic leukemia (APL) remains to be determined." (PMID 31311081, 2019).
Autoimmunity (1 paper, 2022). The occurrence of an immune reaction against the organism's own cells or tissues. "MAGE-A3 and PRAME are rarely expressed in somatic tissue and harbor a low risk for autoimmunity." (PMID 35185883, 2022).
conjunctival melanomas (1 paper, 2024). "The role of PRAME in conjunctival melanoma is less well known, but is being explored as a potential biomarker for early diagnosis and prognosis." (PMID 38338862, 2024).
esophageal cancer (1 paper, 2019). A primary or metastatic malignant neoplasm involving the esophagus. "Indeed, further analyses of TCGA and GTEx data showed that PRAME expression is also upregulated in ovarian and esophageal cancer tissues compared to their normal counterparts." (PMID 30602372, 2019). "GO-disease inference revealed frequent aberration of the PRAME-differentially expressed genes in ovarian and esophageal cancer, suggesting that PRAME and its effectors may also play a role in these solid cancer types." (PMID 30602372, 2019).
Infertility (1 paper, 2011). "Anti-sperm immunity is considered as one of the causes of infertility in humans and it is thus important to clarify the immunological roles of PRAME in male-related functions." (PMID 21347312, 2011).
laryngeal carcinoma (1 paper, 2023). Carcinoma that arises from the laryngeal epithelium. "Furthermore, it was explored whether the high expression of PRAME influenced the prognosis of laryngeal cancer patients." (PMID 36910848, 2023).
lymph node metastasis (1 paper, 2020). "Remarkable positive associations were identified between the PRAME expression and clinicopathological characteristics, including advanced clinical stage (P < 0.001) and positive lymph node metastasis (P < 0.001)." (PMID 33381588, 2020).
Lymphatic Metastasis (1 paper, 2020). Transfer of a neoplasm from its primary site to lymph nodes or to distant parts of the body by way of the lymphatic system. "The stratified data showed that the PRAME overexpression was significantly associated with lymphatic metastasis (OR = 3.14, 95% CI: 1.99–4.97, P < 0.001)." (PMID 33381588, 2020).
melanoacanthoma (1 paper, 2026). A benign, darkly pigmented skin lesion characterized by proliferation of keratinocytes and melanocytes. "This study investigated PRAME expression in melanoacanthomas, with particular emphasis on its relationship with ultraviolet exposure and chronic solar damage." (PMID 41892080, 2026).
mesothelioma (1 paper, 2025). A usually malignant and aggressive neoplasm of the mesothelium which is often associated with exposure to asbestos. "The proteins that were unique to mesothelioma samples (cell line and PE samples) were MAGED4, PRAME, WT1, ACRBP, EPHA2 and SOX11." (PMID 39921204, 2025).
multinodular goiter (1 paper, 2025). Nodular goiter characterized by more than one discrete tissue mass. "A subsequent immunohistochemical study on various DICER1-driven lesions highlighted how PRAME was generally poorly expressed or negative in multinodular goiter nodules or in well-differentiated thyroid tumors." (PMID 40448797, 2025).
myeloid malignancies (1 paper, 2025). "Based on the favorable safety profiles of PRAME as a target antigen and MDG1011 in vitro and in vivo, this TCR-T therapy approach merits further investigation as a potential ACT to fill the unmet medical need for patients suffering from myeloid malignancies." (PMID 39858024, 2025).
NUT carcinomas (1 paper, 2024). "PRAME protein overexpression has also been noted in some NUT carcinomas (D Bell unpublished observations)." (PMID 38315310, 2024).
ocular melanoma (1 paper, 2024). A melanoma that arises from the structures of the eye or ocular adnexa. "The role of PRAME in ocular melanomas and its potential as a therapeutic target represent interesting opportunities." (PMID 38338862, 2024).
prostate carcinoma (1 paper, 2022). A carcinoma that arises from epithelial cells of the prostate gland. "A prognostic model composed of seven protein-coding genes (FOXN4, MGAM, MMP26, ARC, SOX11, PRAME, and VWA5B2) was established, and it was strongly associated with biochemical recurrence following radical prostatectomy in prostate cancer." (PMID 37255653, 2022).
salivary gland carcinoma (1 paper, 2026). A carcinoma that arises from the major or minor salivary glands. "This retrospective study evaluated the expression of three immunologically relevant biomarkers-PRAME, FOLR1, and CLDN18.2-as potential therapeutic targets in salivary gland carcinomas." (PMID 41968569, 2026).
sebaceous neoplasms (1 paper, 2024). "While BCCs and SCCs mostly exhibited weak to moderate nuclear staining for PRAME, sebaceous neoplasms demonstrated cytoplasmic staining, facilitating differentiation between these entities." (PMID 39727621, 2024).
serous ovarian adenocarcinomas (1 paper, 2009). "Even though we did not detect any differences in relation to survival in our analysis, the expression of CLU, CAPG, and PRAME might still be associated with the development and progression of serous ovarian adenocarcinomas." (PMID 19775429, 2009). "In this study, we performed an external validation of four potential prognostic biomarkers, ITGB3, CLU, CAPG, and PRAME, in advanced ovarian serous adenocarcinomas." (PMID 19775429, 2009).
soft tissue tumours (1 paper, 2024). "Regarding soft tissue tumours, a study is reported in the literature of 350 soft tissue tumours of >50 histotypes, in which PRAME immunoreactivity was graded from 0 to 4+ based on the percentage of positive cells." (PMID 38338862, 2024).
spitzoid melanoma (1 paper, 2024). "In contrast, the eight cases that showed positive PRAME expression but were FISH-negative included seven diagnoses of atypical Spitz tumours (AST) and one case was identified as a spitzoid melanoma, representing a discordant case." (PMID 38338862, 2024).
sweat gland neoplasm (1 paper, 2024). A benign or malignant neoplasm arising from the sweat glands. "Further studies are warranted to elucidate the significance of PRAME staining in sweat gland neoplasms and its potential diagnostic and prognostic implications." (PMID 39727621, 2024). "A subset of sweat gland tumors exhibited cytoplasmic PRAME staining, albeit with lower percentages and intensity compared to sebaceous lesions." (PMID 39727621, 2024).
testicular cancer (1 paper, 2024). A primary or metastatic malignant neoplasm that affects the testis. "In conclusion, PRAME is a testicular cancer antigen that serves as an important biomarker and potential therapeutic target in a variety of cancers." (PMID 38338862, 2024).
thymic carcinoma (1 paper, 2020). Thymic carcinoma (TC) is a type of thymic epithelial neoplasm characterized by a high malignant potential. "Thus, it remains unclear whether overexpression of PRAME is TSQCC-specific or thymic carcinoma-specific." (PMID 32704057, 2020).
tumor (174 papers, 2005 to 2026). "From the therapeutic perspective, PRAME and other tumor-associated antigens (TAAs) present favorable targets for immunotherapy." (PMID 40868240, 2025). "SF3B1 mutations were associated with Class 1 tumors (p < 0.0001), PRAME(+) status (p < 0.0001), decreased patient age (p < 0.0001), increased tumor diameter (p = 0.02), and brown iris color (p = 0.008)." (PMID 41387680, 2025). "The expression of PRAME is a marker for an undifferentiated cellular state and has been implicated in the inhibition of tumour cell differentiation and the promotion of proliferation, which can contribute to oncogenesis." (PMID 38338862, 2024). "Because of its association with multiple tumor indications, PRAME is an attractive target for cancer immunotherapy." (PMID 39659431, 2024). "MSAB has also been used in animal experiments; therapy with Wnt inhibitor MSAB partially inhibited the tumor-growth-promoting effect in vivo caused by PRAME overexpression." (PMID 36980687, 2023). "PRAME-deleted tumors showed cytotoxic T cell immune escape and were associated with cold tumor microenvironments." (PMID 35380993, 2022). "Orlando and colleagues have recently reported expression of the tumour-associated antigen PRAME in 82% of MB tumour tissues." (PMID 34195095, 2021). "Our findings suggest that PRAME is a tumour‐associated antigen that can modulate the anti‐tumour immune response." (PMID 34612587, 2021). "The prognostic significance of PRAME expression in UM emerged from a few studies conducted over the past 5 years, which showed that PRAME expression in UM is associated with an increased tumour volume, enhanced metastatic risk and global inferior prognosis." (PMID 35008260, 2021). "Integration of our transcriptomic and immunopeptidomic analyses revealed high-affinity peptides derived from tumor-associated genes such as PRAME, PBK, and several MAGE gene family genes." (PMID 34818552, 2021). "PRAME expression positively correlated with larger tumor diameter and SF3B1 mutations as well as gain of 1q, 6p, 8q, and 9q and loss of 6q and 11q." (PMID 32992823, 2020). "The stratified data showed that the PRAME overexpression was significantly associated with tumour stage (OR = 1.99, 95% CI: 1.48–2.67, P < 0.001)." (PMID 33381588, 2020). "Our data indicated that the PRAME expression was significantly associated with tumour stage (OR = 1.99, 95% CI: 1.48–2.67, P < 0.001) and positive lymph node metastasis (OR = 3.14, 95% CI: 1.99–4.97, P < 0.001)." (PMID 33381588, 2020). "As far as chromosomal alteration is concerned, PRAME+ tumours were strongly associated with 6p loss, 6q loss and 8p gain both in class 1 and class 2 tumours, while 8p loss was associated with PRAME+ status only in class 2 tumours." (PMID 31109147, 2019). "Recently, the cancer-testis antigen PRAME (preferentially expressed antigen in melanoma) has been evaluated as an independent biomarker to predict metastasis risk both in class 1 and class 2 tumours." (PMID 31109147, 2019). "Compared to normal human breast cells, SV-BR-1-GM cells overexpress genes encoding tumor-associated antigens (TAAs) such as PRAME, a cancer/testis antigen." (PMID 29867922, 2018). "8p loss was associated with PRAME+ status only in Class 2 tumors, whereas 8q gain was associated with PRAME+ status in both tumor classes." (PMID 27486988, 2016). "The only features that were significantly associated with PRAME+ status were larger tumor diameter and thickness (Mann-Whitney test, P = 0.01 and P = 0.02, respectively)." (PMID 27486988, 2016). "Consistent with our original dataset, PRAME+ status in the TCGA dataset was associated with larger tumor diameter (P = 0.02)." (PMID 27486988, 2016). "Furthermore, the CL-B class relies heavily on the PRAME regulator, an oncoprotein linked to advanced tumor stages and poor prognosis, highlighting its clinical relevance." (PMID 40234567, 2025).